SAP30L (SAP30 like)
Description:
[Isoform 1]: Functions as a transcription repressor, probably via its interaction with histone deacetylase complexes. Involved in the functional recruitment of the class 1 Sin3-histone deacetylase complex (HDAC) to the nucleolus. Binds DNA, apparently without sequence-specificity, and bends bound double-stranded DNA. Binds phosphoinositol phosphates (phosphoinositol 3-phosphate, phosphoinositol 4-phosphate and phosphoinositol 5-phosphate) via the same basic sequence motif that mediates DNA binding and nuclear import. [Isoform 2]: Functions as a transcription repressor; isoform 2 has lower transcription repressor activity than isoform 1 and isoform 3. [Isoform 3]: Functions as a transcription repressor; its activity is marginally lower than that of isoform 1.
Synonyms: NS4ATP2; FLJ11526
Tractability: PROTAC: UniProt records ubiquitination sites on it; its protein half-life has been measured.
Gene: Protein-coding gene on chromosome 5 (154,445,997 to 154,461,053, forward strand). Ensembl gene ENSG00000164576.
Subcellular location: Nucleus, nucleolus (Isoform 1); Nucleus, nucleolus (Isoform 2); Nucleus, nucleolus (Isoform 3)
Subcellular location (Human Protein Atlas): Nucleoli fibrillar center; Nucleoplasm
Pathways (Reactome):
Chromatin organization: HDACs deacetylate histones
Disease: Potential therapeutics for SARS
Gene expression (Transcription): NoRC negatively regulates rRNA expression
Gene Ontology:
Molecular function: DNA binding; histone binding; non-sequence-specific DNA binding, bending; nucleosome binding; phosphatidylinositol-5-phosphate binding; protein binding; zinc ion binding; transcription coregulator activity
Biological process: negative regulation of cell migration; negative regulation of stem cell population maintenance; negative regulation of transcription by RNA polymerase II; negative regulation of transforming growth factor beta receptor signaling pathway; positive regulation of stem cell population maintenance; regulation of DNA-templated transcription
Cellular component: fibrillar center; nucleolus; nucleoplasm; histone deacetylase complex; nucleus; Sin3-type complex
Genetic constraint (gnomAD): Loss-of-function variants: 9 observed, 19.17 expected, observed/expected ratio (o/e) 0.47, 90% interval 0.28 to 0.82. The upper end of that interval is the gene's LOEUF score, 0.82, which puts it in group 3 of 6, group 1 being the genes least tolerant of losing a copy. Missense variants: 202 observed, 221.5 expected, observed/expected ratio (o/e) 0.91, 90% interval 0.81 to 1.02. Synonymous variants: 89 observed, 89.42 expected, observed/expected ratio (o/e) 1, 90% interval 0.84 to 1.19.
Homologues: Orthologues: chimpanzee SAP30L (100% identical), macaque SAP30L (100% identical), dog SAP30L (99% identical), pig SAP30L (99% identical), rabbit SAP30L (98% identical), mouse Sap30l (97% identical), rat Sap30l (97% identical), tropical clawed frog sap30l (89% identical), zebrafish sap30l (85% identical), guinea pig SAP30L (68% identical), Drosophila melanogaster Sap30 (54% identical). Paralogues in human: SAP30 (70% identical).
Diseases named in the same sentence as SAP30L in open-access papers:
SAP30L is named in the same sentence as 3 diseases in open-access papers, as found by Europe PMC text mining. Sharing a sentence is not in itself a finding about the gene and the disease. The quoted sentences say what the papers report.
tumor (1 paper, 2025). "Specifically, PIWIL4, SATB1, GSE1, NCOR1, SAP30L, ATM, and BMI1 were significantly downregulated in tumor tissues relative to normal controls, while BUB1, CHEK1, MASTL, DNAJC2, UBE2D1, and SSRP1 showed pronounced upregulation." (PMID 41208974, 2025).
SAP30L also shares sentences with these, for which no sentence is quoted: cancer (1 paper); Hypertension (1).